MAGEA10 (MAGE family member A10)
Description:
Not known, though may play a role in embryonal development and tumor transformation or aspects of tumor progression.
Synonyms: CT1.10; MAGE10; MGC10599
Tractability: PROTAC: ubiquitination databases record sites on it.
Gene: Protein-coding gene on chromosome X (152,133,310 to 152,138,578, reverse strand). Ensembl gene ENSG00000124260.
Subcellular location: Nucleus
Subcellular location (Human Protein Atlas): Nucleoplasm; Cytosol
Gene Ontology:
Molecular function: histone deacetylase binding
Biological process: negative regulation of transcription by RNA polymerase II
Cellular component: nucleoplasm; nucleus
Homologues: Orthologues: chimpanzee MAGEA10 (97% identical), macaque MAGEA10 (95% identical), pig MAGEA10 (68% identical), rat Magea10 (50% identical), mouse Magea10 (49% identical), mouse Magea6 (42% identical), mouse Magea5 (41% identical), rat Magea10-ps3 (41% identical), mouse Magea4 (41% identical), mouse Magea3 (40% identical), mouse Magea8 (40% identical), mouse Magea1 (40% identical), and 7 more. Paralogues in human: MAGEA8 (50% identical), MAGEA11 (49% identical), MAGEA1 (47% identical), MAGEA4 (46% identical), MAGEA9 (46% identical), MAGEA9B (46% identical), MAGEC1 (46% identical), MAGEA2 (44% identical), MAGEA2B (44% identical), MAGEB4 (44% identical), MAGEC2 (44% identical), MAGEA12 (44% identical), and 25 more.
Diseases named in the same sentence as MAGEA10 in open-access papers:
MAGEA10 is named in the same sentence as 24 diseases in open-access papers, as found by Europe PMC text mining. Sharing a sentence is not in itself a finding about the gene and the disease. The quoted sentences say what the papers report.
melanoma (12 papers, 2012 to 2023). A malignant, usually aggressive tumor composed of atypical, neoplastic melanocytes. "Evaluating expression in melanomas relative to melanocytes, we observed that two MAGE genes, MAGEA10 and MAGEE1 (MIM: 300759), were significantly upregulated and that several canonical melanocyte and stably expressed genes were downregulated." (PMID 37339630, 2023). "MHC-I AI alleles also uniquely target positions in the melanoma antigen genes MAGEA10 and MAGEE1, which are upregulated in melanoma relative to melanocytes." (PMID 37339630, 2023). "Five different melanoma antigens, MAGEA4, MAGEA10, MART1, TRP1 and MCAM, were co-expressed with the MLV Gag protein in mouse fibroblast cells, and their incorporation into VLPs and localization within the particles were determined." (PMID 27403717, 2016). "In this study, five different melanoma antigens, MAGEA4, MAGEA10, MART1, TRP1 and MCAM, were incorporated into the VLPs and their localization within the particles was determined." (PMID 27403717, 2016). "All five melanoma antigens, the MART1, TRP1, MCAM, MAGEA4 and MAGEA10 proteins were detected in respective VLP’s confirming once again the effective incorporation of recombinant proteins into VLPs induced by overexpression of the MLV Gag protein." (PMID 27403717, 2016).
ovarian carcinoma (8 papers, 2012 to 2024). A malignant neoplasm originating from the surface ovarian epithelium. "In summary, the current SEREX analysis of ovarian cancer led to the isolation of 4 tissue-restricted gene products, including one known CT antigen (KP-OVA-40/MAGEA10)." (PMID 22684412, 2012).
bladder cancer (3 papers, 2022 to 2025). "This included strong upregulation of cancer‐testis antigens (MAGEA3, MAGEA6, MAGEA10) and neuroendocrine‐associated genes such as NEB and NELL2, features linked to higher tumour grade, invasion and lineage plasticity in bladder cancer." (PMID 41425537, 2025). "A data analysis of bladder cancer patients further uncovers the possibilities of utilizing MAGEA2, MAGEA3, MAGEA4, MAGEA6, MAGEA10, MAGEA11, and MAGEA12 members as diagnostic biomarkers for bladder cancer." (PMID 38254738, 2024). "It was found that frequencies of genomic alterations among MAGEA family members in bladder cancer were MAGEA1 1.8%, MAGEA2 1.6%, MAGEA3 1.9%, MAGEA4 1.6%, MAGEA6 2.6%, MAGEA8 1.7%, MAGEA10 2%, MAGEA11, 2.1%, and MAGEA12 2.4%." (PMID 38254738, 2024). "Interestingly, MAGEA2, MAGEA3, MAGEA4, MAGEA6, MAGEA10, MAGEA11, and MAGEA12 exhibited significant differences in their expression in bladder cancer compared to normal bladder samples." (PMID 38254738, 2024).
breast carcinoma (2 papers, 2007 to 2013). "More than two-thirds of breast cancers would be covered by a vaccine directed against just three CTAGs – CTAG1, BAGE1, and MAGEA10 – all of which are known to be targets of cytotoxic-T-lymphocyte responses." (PMID 17650306, 2007). "A vaccine directed against just three antigens known to be capable of eliciting CTL responses (CTAG1, MAGEA10 and BAGE1) would be of potential utility in up to 70% of breast cancers." (PMID 17650306, 2007).
glioma (1 paper, 2015). A benign or malignant brain and spinal cord tumor that arises from glial cells (astrocytes, oligodendrocytes, ependymal cells). "Many of these up-regulated TAPPs are common in gliomas and other brain cancers, such as Aim2, EZH2, GP100, Mage-1, MageA4, MageA10, Sart-1, -3, Trp-1, and Sox2." (PMID 26175925, 2015).
meningioma (1 paper, 2023). A generally slow growing tumor attached to the dura mater. "Regarding HLA class II, 26 antigens were exclusively identified in the peptidome of meningiomas, with MAGEA10, MUTYH, and CABYR being the most frequent (6–15% positive tumors)." (PMID 37368072, 2023).
osteosarcoma (1 paper, 2019). A usually aggressive malignant bone-forming mesenchymal neoplasm, predominantly affecting adolescents and young adults. "In the current study, we show that MAGEA4 and MAGEA10 proteins are incorporated into extracellular vesicles released by mouse fibroblast and human osteosarcoma U2OS cells and are expressed, at least partly, on the surface of released EVs." (PMID 31217903, 2019). "In the current study, we show that MAGEA4 and MAGEA10 proteins are incorporated into naturally occurring EVs released by mouse fibroblast and human osteosarcoma U2OS cells and are expressed on the surface of EVs." (PMID 31217903, 2019). "Most of the cell lines do not express MAGEA proteins, one of the few exceptions is human osteosarcoma cell line U2OS, which expresses several MAGEA proteins including MAGEA4 and to lesser extent MAGEA10." (PMID 31217903, 2019).
pancreatic cancer (1 paper, 2023). "Indeed, our MAGEA DNA vaccine successfully elicits effective T cell activities against each antigen and effectively eliminates GemR tumor cells expressing high levels of MAGEA2, MAGEA3, and MAGEA10 in two distinct mouse models of pancreatic cancer." (PMID 37814317, 2023).
tumor (20 papers, 2008 to 2025). "These included MAGEA3, MAGEA6 and MAGEA10, all cancer‐testis antigens previously associated with higher tumour grade, stage, and risk of invasion in NMIBC." (PMID 41425537, 2025). "Among the neoantigens are well-known genes associated with tumor progression and metastases, such as HAUS3, NSDHL, MAGEA10, FNDC3B, TEAD1, DHX33, PGM5, and MLL2." (PMID 36607962, 2023). "These CTAs were expressed by tumor cells, similar to MAGEA10, MAGEC1, and CTAG1B proteins as demonstrated in our previous study." (PMID 34065388, 2021). "Although pre-ranked GSEA analysis for RP11-366F6.2 returned no significantly gene sets, examining the functional roles of deregulated genes (such as MAGEA4, MAGEA10, HOXD10 and IGF2BP1) in the leading edge set indicated RP11-366F6.2 might be associated with tumor invasion and metastasis." (PMID 32174965, 2020). "Our clinical studies have revealed that the expression of MAGEA, particularly MAGEA2, MAGEA3, and MAGEA10, but not other family members, may play a crucial role in determining tumor growth, chemoresistance, and cancer progression in multiple cancers." (PMID 37814317, 2023). "Due to lack of commercially available murine MAGEA2, MAGEA3 or MAGEA10 antibodies, DT6066 and TB32048 (spontaneous KPC tumor derived cells) cells were chronically exposed to Gem until they became resistant." (PMID 37814317, 2023).
cancer (14 papers, 2013 to 2024). A tumor composed of atypical neoplastic, often pleomorphic cells that invade other tissues. "Given the significance of MAGEA10 in biology, and specifically in cancer, it is important to fully understand the functions of this protein at the molecular level in order to exploit it in translational research." (PMID 38136576, 2023). "To further validate the clinical significance of our findings, we conducted a pan-MAGEA analysis using the KM plotter and TIMER2.0 databases, which includes data from various cancers, summing the expression of MAGEA2, MAGEA3, and MAGEA10." (PMID 37814317, 2023). "Examples of biclusters from this category include the biclusters consisting of genes from the Cancer-Testis antigens family—MAGEA2, MAGEA3, MAGEA6, MAGEA10, CSAG1, CSAG2, CSAG3 (Xq28)/CT45A3, CT45A5, CT45A6 (Xq26.3)." (PMID 31216036, 2019). "We show that the cancer/testis antigens MAGEA4 and MAGEA10 are incorporated on the surface of Gag-based particles when transiently expressed together with the MLV Gag protein." (PMID 27403717, 2016). "Throughout the study, the MLV Gag refers to VLPs obtained by expression of MLV Gag protein without any recombinant cancer antigen, and MART1, TRP1, MAGEA4, MAGEA10 and MCAM mark the VLPs carrying respective cancer antigens." (PMID 27403717, 2016).
MAGEA10 also shares sentences with these, for which no sentence is quoted: head and neck squamous cell carcinoma (3 papers); urothelial carcinoma (3); non-small cell lung carcinoma (2); sarcoma (2); colon cancer (1); HCMV infection (1); hematological cancers (1); hepatocellular carcinoma (1); lung carcinoma (1); lymphoma (1); metastasis (1); serous ovarian carcinoma (1); stomach cancer (1); testicular tumor (1).